METTL3 (methyltransferase 3, N6-adenosine-methyltransferase complex catalytic subunit)
Diseases named in the same sentence as METTL3 in open-access papers (continued):
Sharing a sentence is not in itself a finding about the gene and the disease.
cancer (continued). "As discussed further below, like METTL3 and METTL14, FTO and ALKBH5 are frequently dysregulated in human cancers, suggesting that they may play more critical roles under stress or disease conditions." (PMID 34209046, 2021). "Collectively, the experimental data of our study demonstrated that silencing METTL3 reduced the drug resistance of BC cells to ADR, and promoted cancer cell apoptosis by downregulating miR-221-3p expression through inhibition of the m6A modification of pri-miR-221-3p." (PMID 33420414, 2021). "According to the recent studies, there were 13 m6A regulator genes confirmed to affect cancer progression, including the “writer” (KIAA1429, METTL3, METTL14, RBM15, WTAP, and ZC3H13), the “readers” (HNRNPC, YTHDC1, YTHDC2, YTHDF1, and YTHDF2), and the “erasers” (ALKBH5 and FTO)." (PMID 34179079, 2021). "Unfortunately, selective METTL3/METTL14 inhibitors for cancer therapies are not yet available, but bisubstrate inhibitors are promising small-molecules in that they can be developed to be effective METTL3/METTL14 targeting agents." (PMID 34526985, 2021). "Like METTL3 enzyme, also the ADAR proteins have been indicated as an important player in cancer." (PMID 33509238, 2021). "AML has the highest expression of METTL3 and METTL14 among all cancer types." (PMID 32111216, 2020). "METTL3 facilitates the translation of important oncogenes such as epidermal growth factor receptor (EGFR) and tafazzin (TAZ), a Hippo pathway effector, further regulating cancer cell growth, survival, and invasion." (PMID 32709063, 2020). "METTL3 and METTL14 are the most widely studied m6A regulatory genes in various cancers." (PMID 32547941, 2020). "qRT-PCR showed enhanced expression of METTL3 and TGFβ1 in metastasized lung tumors compared to that in the primary tumors isolated from MMTV-PyMT mice, confirming that METTL3/TGFβ1 triggers cancer progression and metastasis." (PMID 31991845, 2020). "Therefore, it is limited to study the role of METTL3 and METTL14 in cancer only from the perspective of catalyzing m6A modification." (PMID 33159022, 2020). "RNA methyltransferases (such as METTL14, METTL3 and TAP), the demethylases(such as ALKBH5 and FTO), and the binding proteins (such as YTHDF2 and YTHDF1) are often upregulated in a variety of human cancer types to increase the expression of oncogenes and oncoproteins." (PMID 33136551, 2020). "While the roles of m6A modifications in cancer have been extensively reviewed elsewhere, the critical functions of METTL3 in various types of cancer, as well as the potential targeting of METTL3 as cancer treatment, have not yet been highlighted." (PMID 32854717, 2020). "Therefore, it is urgently needed to further clarify the characterization of METTL3 and METTL14 in cancers." (PMID 33159022, 2020). "METTL3 as the core writer, it’s frequently reported to mediate RNA metabolism cooperating with the downstream directly-executive reader YTHDF2 in various diseases especially in cancers." (PMID 33121495, 2020). "The epithelial mesenchymal transition (EMT), a critical process for cancer cell metastasis, is regulated by the m6A writer METTL3, not only in HCC but across diverse cancers." (PMID 32733807, 2020). "Finally, we also provided evidence for the large transcriptome levels of METTL3 and METTL14 as cancer driver genes." (PMID 32211315, 2020). "In our work, we think that MYC can be regulated by both METTL3/IGF2BP2 axis and SOX2 respectively, which might partially explain the elevated expression of MYC in various human cancers." (PMID 31230592, 2019). "Indeed, increasing m6A through knocking down adenosine demethylases (FTO and ALKBH5) or overexpressing adenosine methyltransferases (METTL3 and METTL14) suppressed the cancer cell proliferation." (PMID 29228737, 2017). "Silencing METTL3 displayed a nonnegligible effect on the cilia elongation of cancer cells." (PMID 39535388, 2025).
cancer (continued). "METTL3 also increased the stability of multiple lncRNAs like MALAT1, THAP domain containing seven antisense RNA 1 (THAP7-AS1), small nucleolar RNA host gene 7 (SNHG7) and promotes various cancers progression including glioma, gastric cancer and prostate cancer." (PMID 40510136, 2025). "METTL3 May posttranscriptionally upregulate the levels of inhibitor of DNA binding 2 (ID2) in an m6A/YTHDF2-dependent mechanism, thereby enhancing ID2 mRNA stability and promoting cancer cell proliferative capacity." (PMID 40986143, 2025). "In addition, these APA genes following METTL3 and IGF2BP2 knockdown were enriched in several cancer‐related pathways, such as the Hippo pathway, autophagy, the TGF‐beta pathway, the AMPK pathway and cancers." (PMID 40629911, 2025). "Moreover, METTL3 also regulates the maturation of miR-146a-5p through m6A modification, further activating the NUMB endocytic adaptor protein (NUMB)/neurogenic locus notch homolog protein (NOTCH) 2 signaling pathway to promote cancer cell growth." (PMID 40747121, 2025). "The roles of m6A and METTL3 in ferroptosis are not consistent in cancer cells." (PMID 39800682, 2025). "Since METTL3 can negatively regulate the pGL-SLC7A11 promoter reporter, it indicates that transcription factors are also involved in m6A-regulated transcription of SLC7A11.We found that GATA3 is involved in METTL3-regulated expression of SLC7A11 and ferroptosis in cancer cells." (PMID 39800682, 2025). "Therefore, we hypothesized that combining METTL3 and PARP inhibitors could synergize in treating cancer cells." (PMID 40219966, 2025). "Notably, the METTL3-regulated SRC expression might be cancer type-specific and the relationship between METTL3 and c-Src in other types of cancer remains an open question." (PMID 40612868, 2025). "In addition to FTO inhibitors, the inhibitor of METTL3, STM2457, as a highly efficient and selective inhibitor, with in vivo activity and therapeutic efficacy, marks the first evidence of the effectiveness of RNA methyltransferase inhibitors in cancer therapy." (PMID 39473440, 2024). "Therefore, investigations of the functions and mechanisms of METTL3 in cancer cells and TME might enhance our comprehension of the roles of METTL3 in cancer." (PMID 38322265, 2024). "Mechanistically, METTL3 deletion decreases the transcription efficiency of Forkhead box O3 (FOXO3) via a YTHDF1-dependent fashion and thereby promotes autophagy, a crucial process in multidrug resistance in chemotherapy of cancer, thus ultimately resulting in sorafenib resistance." (PMID 38545555, 2024). "Belonging to the Class I methyltransferase family, METTL3 usually forms stable heterodimer complexes with METTL14 through its methyltransferase activity to mediate m6A methylation, regulates a variety of biological processes and plays several functional roles as an oncogene in cancers." (PMID 39163514, 2024). "Therefore, conducting a larger number of clinical tissue sample studies can provide a more comprehensive understanding of the specific involvement of METTL3 in LUAD, which holds significant implications for elucidating its mechanistic actions in this particular cancer type." (PMID 39497721, 2024). "Moreover, it can regulate cancer cell proliferation and apoptosis by targeting different genes, including mitogen-activated protein kinase kinase kinase 3 (MAP3K3), SRY-box transcription factor 4 (SOX4), and methyltransferase like 3 (METTL3)." (PMID 39062744, 2024). "Additionally, TCGA pan-cancer data revealed a negative correlation between METTL3 and DECR1 expression in LIHC." (PMID 39629121, 2024). "Proper regulation of METTL3 and METTL14 may help restore m6A landmarks to halt cancer progression." (PMID 39006762, 2024).
cancer (continued). "METTL3-mediated m6A modification on the sub-telomeric regions of telomeric repeat-containing RNA (TERRA) led to R-loop formation and promoted homologous recombination (HR), which was essential for the alternative lengthening of telomeres (ALT) pathway and telomere stability in cancer cells." (PMID 37612540, 2023). "Mechanism studies elucidated that METTL3 could increase CBX8 mRNA stability dependent on IGF2BP1, and then CBX8 promotes the transcription of leucine rich repeat containing G protein-coupled receptor 5 (LGR5) to maintain cancer stemness and chemoresistance." (PMID 36810281, 2023). "Therefore, the situation that METTL3-mediated RNA modification and METTL14-mediated RNA modification played an opposite role in the expression of PTEN and cancer progress could be explained." (PMID 36866236, 2023). "Since METTL3 depletion was reported to induce apoptosis and decrease AML development in 2017 82, an increasing number of studies have revealed that apoptosis is regulated by m6A, which plays a crucial role in the occurrence and development of cancer by promoting or suppressing apoptosis." (PMID 37063421, 2023). "METTL3-mediated m6A methylation induces the splicing of estrogen receptor related receptor γ (ERRγ) precursor mRNA, and then ERRγ binds to ATP binding cassette subfamily B member 1 (ABCB1), reinforces its transcription and lowers the sensitivity of cancer cells to numerous anticancer agents." (PMID 37055798, 2023). "In conclusion, akin to METTL3, METTL4, METTL16, WTAP, RBM15/15B, VIRMA, and ZC3H13, the potential influence of YTHDC1, YTHDC2, YTHDF, IGF2BPs, the HNRNP family, eIF3, FTO, and ALKBH3/5 on autophagy is intertwined with their roles in RNA metabolism, collectively regulating autophagy in cancer." (PMID 38148841, 2023). "We previously highlighted that m6A was critical in the progress of epithelial–mesenchymal transition (EMT) since Snail could be modified by m6A in the CDS region and METTL3/YTHDF1 could mediate the expression and translation of Snail mRNA to regulate cancer cells growth and metastasis." (PMID 36260366, 2023). "Our results revealed that in GBM cancer cells, expression of CD274 (PD-L1), PDCD1LG2 (PD-L2), LGALS9 (Galectin-9), and PVR (CD155) were positively correlated with the expression of multiple m6A regulators, especially YTHDF2, YTHDF3, LRPPRC, METTL3, RBM15B, FTO, and ALKBH5." (PMID 35558067, 2022). "m6A modification involves a diversity of regulators, among which, methyltransferase-like proteins, METTL3 and METTL14, are believed to be the most important m6A initiators and have been proved to perform critical roles in various diseases, especially human malignant tumors." (PMID 35305660, 2022). "In prostate cancer, METTL3 improves the YTHDF2–HNRNPD-recognized degradation of ubiquitin-specific peptidase 4 (USP4) by mediating m6A modification on A2696 and then maintains the ubiquitin of ELAV-like RNA-binding protein 1 (ELAVL1), giving rise to the migration and invasion of cancer cells." (PMID 35804965, 2022). "Although METTL3 is reported to promote translation in human cancer cells independent of its catalytic activity and m6A readers, the METTL3 knockdown resulted in a better association of our candidate mRNAs with polysomes, especially PHLDA1, PIDD1 and PMAIP1, under cisplatin treatment conditions." (PMID 36497162, 2022). "Furthermore, the localization of WTAP in nuclear speckles and the formation of a complex with METTL3 and METTL14 need to be further investigated, since this knowledge may be useful for understanding the role of m6A modification in cancer biology." (PMID 36207306, 2022). "Thus, we suggest that among all the m6A regulators, METTL3 and METTL14 could be potential prognostic markers in cancers." (PMID 36347025, 2022). "Consequently, these data suggest that METTL3 and METTL14 may serve as potential therapeutic targets and facilitate the development of new strategies to sensitize cancer cells to DNA-damaging agents in HCC." (PMID 35223847, 2022).
cancer (continued). "Kaplan–Meier analysis indicated that higher ADAR1 and METTL3 expression levels are correlated with shorter overall survival, which implies that both ADAR1 and METTL3 could promote human tumorigenesis and cancer development." (PMID 36077054, 2022). "m6A methylation requires multiple protein complexes in the cell to complete, including writers (METTL3, METTL14, and WTAP), erasers (ALKBH5), and readers, among which METTL3 is involved in cancer progression by regulating the expression of a variety of cancer-related genes." (PMID 36347844, 2022). "However, WTAP expression was not significantly altered by functional depletion of METTL3, as has been reported in other cancer cell types." (PMID 36733939, 2022). "Moreover, proteins responsible for m6A modification, including writers (such as METTL3/14), erasers (such as FTO and ALKBH5), and readers (such as YTHDF1/2/3), have been found to be overexpressed and promote the initiation and development of many cancer types." (PMID 35986274, 2022). "However, the precise role of METTL3 in chemotherapy resistance of cancer cells and its downstream targets have not been fully understood." (PMID 34514103, 2021). "As c-MYC overexpression has been extensively reported as a feature conferring chemoresistance to cancer cells, we can hypothesize that the reduced c-MYC protein levels observed after METTL3 silencing could represent the determinant allowing sensitization to cisplatin treatment." (PMID 34530916, 2021). "Unlike METTL14, METTL3 had been considered as a cancer-promoting gene in various types of cancer." (PMID 34476213, 2021). "Previous studies have also shown elevating m6A regulator METTL3 levels could increase the RNA modification of ZBTB4 and decrease levels of ZBTB4 mRNA, which in turn increase aneuploidy and genome instability across many frequent human cancers." (PMID 35003079, 2021). "Additionally, we observed that METTL3 is involved in the modulation of Notch signaling pathway (including METTL3 DLL3, HES1, and NOTCH3 genes) (q-value < 0.05), which plays an important role in tumorigenesis and cancer development." (PMID 34589481, 2021). "However, METTL3 expression was no differentially expressed between cancer tissues and normal tissues." (PMID 33926554, 2021). "As a result, the roles of PP2Acα and METTL3 in malignant tumors may be very different, but there has been no research on the correlations between them when it comes to GC." (PMID 34485508, 2021). "METTL3-mediated methylation can also enhance the stability of lncRNA FAM225A, which regulates the expression of ITGB3 by binding to miR-590-3p and miR-1275 as ceRNA, and thus activates the FAK/PI3K/AKT signalling pathway and promotes the invasion and migration of cancer cells." (PMID 35004679, 2021). "However, as METTL3 and METTL14 have to form a heterodimer to induce m6A methylation, it seemed to be contradictory for two components of a functional complex demonstrated definitely opposite effects on progression of cancer cells." (PMID 32111213, 2020). "However multiple functions of Mettl3 methyltransferase lead to the lack of correlation, as Mettl3 possesses pro-and anti-oncogenic roles in different types of cancer." (PMID 32344536, 2020). "In addition, METTL3 was reported to promote the translation of important oncogenes in human cancers independent of its catalytic activity and m6A binding proteins." (PMID 33159022, 2020). "Furthermore, Kaplan-Meier, meta-analysis and univariate Cox assay showed that the expression of m6A members including METTL3, METTL14, WTAP and FTO but not their gene mutation and amplification, was tightly associated with cancer progression and poor survival." (PMID 30953473, 2019). "However, previous research has explored the role of METTL3 mainly in established HCC using cancer cell lines or xenograft models, which could not fully recapitulate the early stages of malignant transformation." (PMID 40103332, 2025).
cancer (continued). "Indeed, STC-15, an orally bioavailable small molecule inhibitor of METTL3 in Phase 1 clinical study, can restrain the growth of AML cell lines and patient-derived AML samples with sub-micromolar to 1 micromolar IC50 values through activation of anti-cancer immune responses." (PMID 38322265, 2024). "Therefore, speculating that inhibitors of METTL3, IGF2BP, FTO, and ALKBH may be promising targets for cancer therapy is reasonable, and moreover, combination of these inhibitors with PD-1 inhibitors may enhance the efficacy of anti-PD-1 therapy to overcome drug resistance." (PMID 37485079, 2023). "The identification of Mettl3, as a positive regulator of DC function and TLR4 signaling, may have great relevance to the pathogenesis of diseases related with DC dysfunction, and may facilitate cancer immunotherapy, such as adoptive infusion of DC vaccine or design of potent cellular adjuvant." (PMID 31015515, 2019). "All these data indicated that GATA3 was involved in the negative effects of METTL3 on transcription of SLC7A11 and ferroptosis activity of cancer cells." (PMID 39800682, 2025). "Collectively, these data suggest that METTL3, rather than ALKBH5 or METTL4, is responsible for m6A-triggered erastin-induced ferroptosis in cancer cells." (PMID 39800682, 2025). "We observed that WTAP, METTL3 and METTL14 were significantly upregulated in cancer vs. normal tissues, with METTL3 showing the most significant deregulation." (PMID 34530916, 2021). "Interestingly, although WTAP, METTL3, and METTL14 are core components of the same m6A methyltransferase complex, they do not necessarily exert identical biological effects across cancers." (PMID 41301778, 2025). "Although the relationship between METTL3 and the ERK signaling pathway in cancer has not been established for the first time, a very limited number of studies have been carried out in the past to reveal how METTL3/ERK axis promotes the progression of drug resistance in PCa." (PMID 37095108, 2023). "Surprisingly, we find that several commonly studied RNA modification enzymes such as METTL3 or FTO are not significantly upregulated in most cancer types, whereas several less-characterized RMPs, such as LAGE3 and HENMT1, are dysregulated in many cancers." (PMID 32375858, 2020). "However, ruxolitinib could not suppress the effect of METTL3 depletion-mediated VSV-ΔM51 inhibition when it was added only post-infection, suggesting that cancer cells were in a fully active and irreversible intrinsic antiviral state before infection." (PMID 40214229, 2025).